CXCR5 (C-X-C motif chemokine receptor 5)
Diseases named in the same sentence as CXCR5 in open-access papers (continued):
Sharing a sentence is not in itself a finding about the gene and the disease.
viral infection (37 papers, 2015 to 2025). "IL‐6 deficiency results in the severe reduction of CXCR5+BCL6+ early Tfh cells in vivo within 72 hours of an acute viral infection." (PMID 34032001, 2021). "Circulating T follicular helper (cTFH) cells, identified by the expression of the chemokine receptor CXCR5, are critical for providing help to B cells to produce effective antibody responses against viral infections." (PMID 40906527, 2025). "In mice models, CXCR5+CD8+ T cells can function as memory stem cells in chronic viral infections and maintain virus-specific CD8+ T cell production." (PMID 38426098, 2024). "Previous studies have demonstrated that CXCR5+CD8+ T cell levels appear elevated in viral infections and tumors." (PMID 38426098, 2024). "Given the important roles of T follicular helper (Tfh) cells in vaccination and T helper 1 (Th1) cells in viral infection, we examined spike‐specific circulating Tfh (cTfh, CXCR5+) and Th1 (CXCR5−CXCR3+) cells." (PMID 36639826, 2023). "In contrast, the frequency of CXCR5+SMATA cells are comparable at different periods of acute viral infection." (PMID 37829505, 2023). "At the early time of viral infection, CXCR5+SMATA cells equally upregulate in both acute infection and chronic infection." (PMID 37829505, 2023). "During viral infection and cancer, CXCR5 expression on CD8 T cells generally is indicative of progenitor memory stem-like exhausted cells, which are more responsive to immune checkpoint blockade therapy." (PMID 36314014, 2022). "Overall, these results demonstrate that CXCR5+CD8+ T cells shape the humoral response to peripheral viral infection, promoting IgG2c class switching in response to IAV." (PMID 34326833, 2021). "Recent studies have reported the emergence of CD8+ T cells expressing the chemokine receptor CXCR5 during chronic viral infection." (PMID 33531395, 2021). "The frequency and numbers of CD44+CXCR5+ TFH cells were significantly diminished in Mettl3fl/flCd4-Cre mice compared with those in their control littermates on day 8 post viral infection." (PMID 33637761, 2021). "Lineage commitment to TFH lineage has occurred on day 3 post viral infection, as detected by Bcl-6+CXCR5+ cells." (PMID 33637761, 2021). "In the context of chronic follicular-trophic viral infections, CXCR5+CD8+ T cells control infection through killing infected cells in the follicular microenvironment, eliminating viral reservoirs and maintaining the response against chronic infection." (PMID 34326833, 2021). "This is in line with an NFAT dependence for CXCR5 expression also in TFH cells upon acute viral infection or repetitive immunizations (R. Erapaneedi, unpubl)." (PMID 35069572, 2021). "With these ferret-specific CXCR5 and PD-1 antibodies, these questions can be investigated, including longitudinal tracking of Tfh activity following virus infection." (PMID 33479388, 2021). "Here, we demonstrate that in response to protein immunisation and peripheral viral infection, CXCR5+CD8+ T cells shape the antibody response in vivo." (PMID 34326833, 2021). "In 11q23.3, rs75438046 maps to the 3′ UTR of CXCR5, which controls viral infection in B cell follicles, and BCL9L, a translocation target in acute lymphoblastic leukemia and transcriptional activator of the Wnt/β-catenin cancer signaling pathway." (PMID 33109261, 2020). "Generally, we were able to confirm that activated CXCR5− cTmem cell subsets expressed their subset‐determining cytokines on day 14 after yellow fever vaccination." (PMID 32419947, 2020). "CXCR5+ T cells were described as “less exhausted” and responders to check-point blockade in chronic viral infection." (PMID 32579593, 2020). "In humans at least, viral-specific or tumor infiltrating CXCR5+ CD8 T cells likely utilize cytolytic mechanisms to control viral infection and tumor growth in secondary lymphoid organs, ectopic GC, and the tumor microenvironment." (PMID 31275308, 2019).
viral infection (continued). "Viral infection sets in motion a cascade of immune responses, including both CXCR5+CD4+ T follicular helper (Tfh) cells that regulate humoral immunity and CCR5+CD4+ T cells that mediate cell-mediated immunity." (PMID 28553284, 2017). "CXCR5+ CD8 T cells have been predominately explored in the context of chronic viral infections." (PMID 31275308, 2019). "Thus, Stat5 deficiency in CD8+ T cells leads to increased GC B cells and CXCR5+PD-1+CD8+ T cells during acute viral infection." (PMID 31562329, 2019). "The first approach subdivides activated CD4+ T cells into CXCR6+CXCR5- Th1-like cells and CXCR6-CXCR5+ Tfh-like cells at the peak of immune response during viral infection." (PMID 40391228, 2025). "We further included the analysis of peripheral CD45RAneg CD4+CXCR5+ CXCR3neg T follicular helper (Tfh) cells, since they produce large amounts of IL-21 cytokine to sustain both CD8 and B cell immunity during viral infections such as HIV-119,39,40." (PMID 39709477, 2024). "These chemokines include SDF-1α, MCP-2, MCP-4, MIP-1α, and Eotaxin-1, which bind either to CXCR4, CXCR5, CCR5, or CCR3 and regulate viral infection." (PMID 36851142, 2023). "Overall, results from the different animal models of viral infections suggest CNS infiltrating B cells during viral infection migrate into the CNS in a CXCR3-, CXCR5-, and CCR7-dependent manner whose ligands are also upregulated within the CNS." (PMID 33224101, 2020). "In response to acute viral infection, virus-specific CD4 T cells differentiate into either CXCR5-positive follicular helper T (TFH) cells or CXCR5-negative TH1 cells (16, –, 18)." (PMID 32999031, 2020). "In summary, based on the OVA mouse model that reflects the early stages of chronic hepatotropic viral infection, we have shown that the intrahepatic pool of exhausted Ova-specific CD8+ T cells consists of a specialized subpopulation of CXCR5+ CD8+ T cells." (PMID 33613516, 2020). "Studies done in murine models of neurotropic viral infections indicate that B cells enter the CNS during acute viral infection with early infiltrating B cells expressing CXCR3 and CXCR5 (among others) and upregulation of the corresponding ligands in the CNS." (PMID 33224101, 2020). "CXCR5+ CD8 T cells express decreased grzma, grzmb, and prf1 gene expression when compared to CXCR5- CD8 T cells in viral infection." (PMID 31275308, 2019). "Our data also indicated for the first time in the context of viral infection that Tfh cells express KLF2 and Foxo1, which are inhibitory transcriptional factors responsible for arresting CXCR5 and Bcl-6 expression." (PMID 26640894, 2015). "These chemokines likely facilitate faster lymphocyte and monocyte-derived cell infiltration into the lungs, reflected by earlier upregulation of chemokine receptors CCR4, CCR5, and CXCR5, than seen with PJ73 and VR2332, helping counter viral infection and restore lung homeostasis." (PMID 40459260, 2025). "Including outliers yielded additional immune function–related genes, including those responsive to viral infection (CCL20, CXCR5, MX2), suggesting that these 2 samples may represent a more highly inflammatory state." (PMID 41212059, 2025). "Furthermore, studies assessing the B cell response in the presence of OT-I or Cxcr5-/- OT-I cells revealed that CXCR5+CD8+ T cells shape the antibody response to protein immunisation and peripheral viral infection, promoting class switching to IgG2c in responding B cells." (PMID 34326833, 2021). "Thus, irrespective of viral infection and host species, CXCR5+ CD8 T cells maintain cytolytic capacity in both the blood and lymph node in humans and mice." (PMID 31275308, 2019). "Firstly, we show that CXCR5+CD8+ T cells are generated in vivo in acute responses to protein immunisation and peripheral viral infection, settings where there is no infection in the follicular microenvironment." (PMID 34326833, 2021).
viral infection (continued). "In contrast to CXCR5− Treg cells, the frequency of CD38‐expressing cTfr cells was similar at all time points investigated and did not increase in response to yellow fever vaccination." (PMID 32419947, 2020). "Finally, we could detect CXCR5+PD‐1+ CD8 T cells in antigen‐specific T‐cell populations toward chronic viral infections (EBV), but not an acute viral infection (FLU), indicating that chronic antigen stimulation could be required for CXCR5+PD‐1+ CD8 T cells to develop, as is the case in mice." (PMID 33098668, 2021).
rheumatoid arthritis (35 papers, 2005 to 2026). A chronic, systemic autoimmune disorder characterized by inflammation in the synovial membranes and articular surfaces. "Furthermore, CXCR5 has been associated with other similar immune‐mediated diseases through GWAS studies, such as rheumatoid arthritis and inflammatory bowel disease." (PMID 36281738, 2023). "Our data further support CXCR5+Th17 cells as pathogenic players in rheumatoid arthritis." (PMID 28004828, 2016). "The CXCL13/CXCR5 axis facilitates endothelial progenitor cell homing and angiogenesis during rheumatoid arthritis progression." (PMID 36739468, 2023). "A similar population of PD‐1+CXCR5− extrafollicular Th cells, termed Tph cells, have been reported as driving autoantibody production in a mouse model of rheumatoid arthritis and in human SLE." (PMID 36069030, 2022). "Decreased levels of DP cells and increased frequency of CXCR5+DP CD8+ T cells were found in rheumatoid arthritis patients in comparison to age‐matched controls." (PMID 31755098, 2020). "The top 50 DEG include genes with variants previously associated with SS (CXCR5), SLE (CXCR5, PPP2CA, and TCF7), and rheumatoid arthritis (FCRL3)." (PMID 32650575, 2020). "A subset of CXCR5− T cells, termed T peripheral helper (Tph) cells, which drive B cell differentiation, have been identified in ectopic lymphoid structures in established rheumatoid arthritis synovial tissue." (PMID 36270740, 2022). "Moreover, rheumatoid arthritis patients have higher levels of CD4+PD-1+CXCR5+ Tfh cells in peripheral blood than healthy controls, and the frequency of CD4+ICOS+CXCR5+ Tfh cells is linked with DBA/1 mice undergoing CIA." (PMID 34203838, 2021). "In our study, there were six novel loci outside of this region where genetic variation may influence rheumatoid arthritis risk via changes in DNA methylation (TTC34, MMEL1, AFF3, IRF5, CXCR5 and PGAP3)." (PMID 29893838, 2018). "We analyzed proportions of Th1 (CXCR3+), Th17 (CCR6+) and TfH (CXCR5+) cells within the CD4+CD45RO+ activated/memory population of a cross sectional group of seropositive Rheumatoid Arthritis patients on stable therapy (Cohort 1), compared to age and gender-matched healthy controls." (PMID 28004828, 2016). "Here, we report that in patients with rheumatoid arthritis (RA), excessive generation of CXCR5+PD-1+ memory Tfh cells was observed and the frequency of memory Tfh cells correlated with disease activity score calculator for RA (DAS28)." (PMID 29915585, 2018). "In the present study we investigated the role of the CXCL13/CXCR5 axis in the pathogenesis of rheumatoid arthritis (RA) and specifically addressed the impact of CXCR5-mediated T and B cell migration in this disease." (PMID 28827539, 2017). "For histology, rheumatoid arthritis synovial sections were prepared for Opal multispectral immunofluorescence with anti-CD45RO, CD20, PD-1 and CXCR5 antibodies." (PMID 36270740, 2022). "Further work is needed to investigate the expression of other chemokine receptors such as CXCR5, which was shown to be negatively correlated with the expression of CD183 on rheumatoid arthritis patient’s B cells." (PMID 23840845, 2013). "Third, 5/7 sibling pairs had consistent dysregulation of CXCR5 being down-regulated in PBC lymphocytes, which may reflect a compartmentalization of CXCR5+ cells within the liver or may reflect the chronic activation of B cells, as reported in rheumatoid arthritis." (PMID 24734033, 2014).
lymphoma (31 papers, 2010 to 2025). A malignant (clonal) proliferation of B- lymphocytes or T- lymphocytes which involves the lymph nodes, bone marrow and/or extranodal sites. "The development of ectopic lymphoid structures in the salivary glands, a defining feature of Sjögren’s Syndrome and a recognized risk factor for the onset of lymphoma, has been connected to elevated CXCR5 expression." (PMID 40321894, 2025). "In a murine CLL model, CXCR5-deficiency impaired nodal homing and profoundly reduced lymphoma progression." (PMID 33431832, 2021). "Our data suggest CXCR5 targeting for improved immunotherapy of nodal B-NHL by eliminating lymphoma-associated Tfh cells along with the lymphoma cells." (PMID 33431832, 2021). "In non‐POD24‐FLs, weak CCR3, CXCR3, and CXCR4 expression was observed in 50%, 11.8%, and 40% of lymphoma cells, respectively, while moderate CXCR5 and strong CCR7 expression was detected in 68.3% and 50%." (PMID 40896244, 2025). "We found that GC-derived lymphomas contain a sizable number of PD-1+CXCR5+ TFK cells among the TFH cells and among the cytotoxic CD4+ T cells, respectively." (PMID 41030456, 2025). "CXCR5 is frequently expressed on B-cell lymphoma, allowing for targeted delivery of the nanocapsulated antibody to CXCR5-expressing lymphoma cells." (PMID 35890248, 2022). "Overall, our results emphasize that CXCR5 is an attractive alternative target for lymphoma entities that cannot effectively be controlled by CD19 CARs." (PMID 33431832, 2021). "Several other genes are members of the family of known lymphoma drivers, such as CXCR5, HIST2H3D, ID2 and IRF1." (PMID 33945543, 2021). "Here, the authors generate CAR-T cells against CXCR5 and show they inhibit tumour growth by depleting both B and follicular T helper cells in lymphoma models." (PMID 33431832, 2021). "In a xenograft lymphoma mouse model, continuous anti-CXCR5 antibody treatment retarded tumor growth." (PMID 33431832, 2021). "The tumor-supportive CXCR5 interaction prompted us to interrogate CXCR5 as a target aiming at disrupting the CXCR5-dependent lymphoma cell dissemination and tumor-stroma interaction." (PMID 33431832, 2021). "Collectively, anti-CXCR5 CAR-T cells provide a promising treatment strategy for nodal B-NHLs through the simultaneous elimination of lymphoma B cells and Tfh cells of the tumor-supporting TME." (PMID 33431832, 2021). "The CXCR5 CAR not only endowed T cells with antigen recognition on lymphoma cell lines, but also on a large number of primary patient-derived FL, B-CLL, MCL, and MZL samples." (PMID 33431832, 2021). "We and others showed that CXCR5 expression is particularly high on lymphoma entities that depend on cognate interactions with the stromal microenvironment in lymphoid tissues, i.e. FL, CLL, and MCL2,24,25,39–43." (PMID 33431832, 2021). "In accordance, CXCR5 CAR-T cells showed a higher reactivity toward these lymphoma entities in vitro in comparison to CD19 CAR-T cells." (PMID 33431832, 2021). "CXCR5 is not only expressed on mature B cells and their malignant counterparts, but also expressed in the lymphoma niche by Tfh cells that are reported to sustain lymphoma progression foremost in FL and B-CLL36–38." (PMID 33431832, 2021). "Abnormally high levels of CXCR5 and CXCL13 in the serum of lymphoma patients are significantly associated with poor prognosis." (PMID 33381455, 2020). "Unexpectedly within the CD4+CXCR5+CCR6+ population there were significant reductions in CCR6 expression in lymphoma patients as compared to normal subjects." (PMID 29293620, 2018). "Although there is no direct data about the interaction of CXCL13 with CXCR5 in lymphoma cells of ENKTL, a previous in vitro study with AIDS-related non-Hodgkin lymphoma cell lines demonstrated migration of lymphoma cells expressing CXCR5 toward CXCL13." (PMID 25966773, 2015).
lymphoma (continued). "Studies show certain lymphomas express CXCR5 along with CCR7 in malignancies which experience frequent metastasis to the lymph nodes suggesting a role of CXCR5 in lymph node metastasis." (PMID 24259307, 2013). "Our results show that CXCR5 was co-expressed on CD20-positive lymphoma cells in the PCNSL group." (PMID 36233057, 2022). "CXCR5 is particularly suitable as target in CAR-T cell therapy of lymphoma because of a threefold therapeutic mechanism, namely (i) prevention of tumor cell homing, (ii) direct lymphoma cell elimination, and (iii) abrogation of a tumor-promoting stroma function." (PMID 33431832, 2021). "Stimulation of the CAR-T cells with clonal cell lines expressing graded amounts of CXCR5 demonstrated a sufficiently high avidity for CXCR5 levels found on primary B-NHLs and CXCR5-positive lymphocytes thereby making the CXCR5 CAR suitable for lymphoma targeting." (PMID 33431832, 2021). "Additionally, the CAR T cells could target CXCR5 expressed on T follicular helper cells (Tfh) cells in the lymphoma niche." (PMID 39335157, 2024). "This study focused solely on the expression of CXCR5 and LAG‐3 in peripheral blood CD8+ T cells, as we were unable to obtain lymphoma and normal lymphoid tissue samples." (PMID 40091778, 2025). "In POD24‐FLs, weak CXCR3 and CXCR4 expression was found in 13.33% and 40% of lymphoma cells, with moderate CCR3 and CXCR5, and strong CCR7 in 50%, 70%, and 50%, respectively." (PMID 40896244, 2025). "We found that CXCR5 is widely expressed in neoplastic TFH cells, except in TFHL-NOS, and represents a specific marker of this lymphoma entity." (PMID 38203606, 2023). "In this study, we were able to show that CD20-positive lymphoma cells in a PCNSL PDX homing mouse model with a PVRL phenotype co-express the chemokine receptors CXCR4, CXCR5 as well as CD44 in comparison to a SCNSL PDX mouse model." (PMID 36233057, 2022). "At the time of relapse, CXCR5 antigen was still expressed on remaining tumor cells, which contrasts to the results from anti-CD19 CAR-T cell-treated lymphoma-bearing mice." (PMID 33431832, 2021). "CXCR5 CAR-T cells killed FL, CLL, and MCL cells more effectively than CD19 CAR-T cells, demonstrating superior anti-lymphoma cell activity." (PMID 33431832, 2021). "Not only do the CXCL13+ and/or CXCR5+ malignant lymphocytes (B cells and Tfh cells) promote the accumulation and proliferation of lymphoma cells, but so do the CXCL13+ FDC and circulating CXCR5+ CD4+ T cells." (PMID 34947813, 2021). "We propose that CXCR5 CAR-T cells will abrogate cTfh and follicle-located Tfh cells together with malignant B cells and by that, simultaneously target the TME and lymphoma cells." (PMID 33431832, 2021). "Anti-CXCR5 CAR-T cells eradicate B-NHL cells and lymphoma-supportive Tfh cells more potently than CD19 CAR-T cells in vitro, and they efficiently inhibit lymphoma growth in a murine xenograft model." (PMID 33431832, 2021). "A representative number of patient-derived primary lymphoma cells from FL, CLL, MCL, and marginal zone lymphoma (MZL) were analyzed for the level of CXCR5 surface expression." (PMID 33431832, 2021). "A similar analysis on CD4+CXCR5+CCR6+ (cTfh1/17 and cTfh17) populations also confirms increased PD1 expression in lymphoma patients." (PMID 29293620, 2018). "As few mouse models of AIDS-lymphoma currently exist, our aim in these studies was to create a mouse/human xenograft model of AIDS-BL and to evaluate CXCR5 and CXCL13 expression in this model." (PMID 23936541, 2013). "Further studies are needed to more definitively define the role of the CXCR5/CXCL13 axis, both in murine models, and in human AIDS-lymphoma." (PMID 23936541, 2013). "Here, we show that lymphoma samples contain cytotoxic CD4+ T cells, which were predominantly NKG7/TIA-1+GZMK+ TFH-like in FL and TIA-1+GZMK+ and/or GZMB+ within the CXCR5+PD-1+ and CXCR5–PD-1+ subpopulations of DLBCL." (PMID 41030456, 2025).